TRPA1 (transient receptor potential cation channel subfamily A member 1)
Diseases named in the same sentence as TRPA1 in open-access papers (continued):
Sharing a sentence is not in itself a finding about the gene and the disease.
ischemia (continued). "In a model of ischemic stroke, endothelial cell specific TRPA1-knockout animals exhibited larger infarct sizes, supporting the view that TRPA1 activation by endogenous agonists generated during ischemia can have protective effects as well." (PMID 31547502, 2019). "In contrast, global knockout of TRPA1 results in less myocardial injury in a mouse model of IRI (30 min of ischemia followed by 24 h of reperfusion)." (PMID 31680989, 2019). "The OP-induced elevation of [Ca2+]i in native neurons is in line with the essential roles of TRPA1-mediated Ca2+ influx for myelin damage in ischemia." (PMID 28894590, 2017). "The paw-withdrawal response to von Frey filament stimulation in WT and TRPA1-KO mice were similarly reduced during hindlimb ischemia and after reperfusion." (PMID 26983498, 2016). "This review provides a comprehensive analysis of recent studies investigating the involvement of TRPA1 channels in various cardiovascular diseases, including myocardial infarction, ischemia-reperfusion injury, myocardial fibrosis, and response to environmental toxins." (PMID 39323758, 2024). "The transient receptor, TRPA1, is found to be augmented in ischemia-induced cell death induction." (PMID 36986445, 2023). "For confirmatory purposes, we aimed to explore whether TRPA1−/− mice show altered myocardial damage due to ischemia, assuming the effects to have the same direction as pharmacological inhibition." (PMID 36768836, 2023). "Importantly, TRPA1 activity is one of the plausible molecular mechanisms to explain the abnormal sensations during and after hypoxia induced by ischemia, which leads to the release of hydrogen peroxide (H2O2) and nitric oxide (NO) into the tissue." (PMID 35069559, 2021). "As such, we aimed to determine whether the presence or activation of TRPA1 protects against ischemia-induced cell death." (PMID 31161862, 2019). "In summary, the net importance of TRPA1 is unclear, and might even depend on level, extent and duration of ischemia." (PMID 31547502, 2019). "In an in vivo rat model of myocardial IRI (30 min of ischemia followed by 2 h of reperfusion), the administration of the TRPA1 agonist reduced the myocardial infarct size before ischemia and reperfusion, and TRPA1 channel inhibition also blocked the infarct size-sparing effects of morphine." (PMID 31680989, 2019). "Therefore, activation of the TRPA1/Akt/eNOS pathway attenuates ischemia-induced CM cell death." (PMID 31161862, 2019). "Thus, TRPA1 activation in human ischemia might turn out to be a two-edged sword, where both favourable and unfavourable effects result from TRPA1 modulation." (PMID 31547502, 2019). "Our results suggest that transient hindlimb ischemia/reperfusion-evoked spontaneous licking, i.e. painful dysesthesia, is caused by ROS-evoked activation of TRPA1 sensitised by hypoxia through inhibiting PHD-mediated hydroxylation of a proline residue in TRPA1." (PMID 26983498, 2016). "BRL, in addition to iloprost which is routinely being used clinically and treatment modalities that includes BRL, TRPA1, and TRPC1 need to be investigated in detail for the effects on the ischemia originated diseases." (PMID 34174803, 2021). "Freshly isolated CMs from wild-type (WT) or TRPA1 knockout (TRPA1-/-) mouse hearts were treated with AITC (100 μM) and prepared for immunoblot, NO detection or ischemia protocols." (PMID 31161862, 2019). "The present review article shows that TRPA1, similar to other TRP channels may either have protective or deteriorative functions during ischemia." (PMID 38333756, 2024). "First, calcitonin gene-related peptide was investigated, as this neuropeptide is released by sensory neurons upon the activation of TRPA1 and TRPV1, which are sensors of noxious compounds including reactive oxygen species and acidosis, that occurs during ischemia." (PMID 39200320, 2024).
ischemia (continued). "The only available in vivo study at the time this study was planned showed that the TRPA1 activators ASP 7663 and optovin applied before ischemia reduced infarct size in a rat model of acute myocardial infarction with 30 min ischemia followed by 2 h reperfusion." (PMID 36768836, 2023). "Regarding TRPA1−/− sensory neurons, the effect of IR on the survival probability of CM tended to differ between the three conditions with no sensory neurons, wild type sensory neurons and TRPA1−/− sensory neurons (ischemia*sensory neuron interaction p = 0.07)." (PMID 36768836, 2023). "The present findings suggest that ROS produced by transient hindlimb ischemia/reperfusion evokes spontaneous licking through activation of TRPA1, but not TRPV1." (PMID 26983498, 2016). "This suggests that TRPA1 might be involved in myocardial damage in response to ischemia, however, clinical studies have not been performed." (PMID 31547502, 2019). "However, we demonstrate that, although Akt and eNOS do not play a role in the TRPA1-induced increases in CM [Ca2+]i and contractile function, eNOS appears to mediate the TRPA1-elicited attenuation of ischemia-induced cardiac cell death." (PMID 31161862, 2019). "In addition, TRPA1 deletion in C57BL/6 mice could not protect the heart from ischemia." (PMID 38333756, 2024).
diabetic neuropathy (20 papers, 2013 to 2024). A chronic, pathological complication associated with diabetes mellitus, where nerve damages are incurred due to diabetic microvascular injury involving small blood vessels that supply these nerves, resulting in peripheral and/or autonomic nerve dysfunction. "Painful diabetic neuropathy has been linked to TRPA1 in animal studies using antagonists, but to our knowledge data have not yet been reported in knockout animals." (PMID 31969645, 2020). "This suggests a role of TRPA1 variants in thermal sensation; however, based on the limited number of samples, it is not possible to draw a definite conclusion, especially as abnormal thermal sensation is common in patients with diabetic neuropathy." (PMID 35806193, 2022). "GRC17536, another TRPA1 antagonist, showed promise in reducing pain scores in patients with painful diabetic polyneuropathy, highlighting the potential clinical benefits of targeting TRPA1 for pain management." (PMID 39598351, 2024). "A phase two randomized, controlled, double-blinded clinical trial evaluating the TRPA1 blocker ISC-17536 (Glenmark Pharmaceuticals) as monotherapy for painful diabetic neuropathy was published recently." (PMID 36733462, 2023). "TRPA1 inhibitors are being actively considered in clinical trials for postoperative pain and diabetic neuropathy." (PMID 35921423, 2022). "But this inhibition of TRPA1 activity by AMPK activation was seen to be a helpful factor in preventing diabetic neuropathy as it led to the deterrence of mechanical allodynia in diabetic mice." (PMID 34912298, 2021). "TRPA1 antagonists have shown reduced diabetic neuropathy development in animals, but detailed studies are still required." (PMID 34912298, 2021). "Of note, TRPA1 antagonist GRC 17536 has been studied in a phase II clinical trial for painful diabetic neuropathy (NCT01726413)." (PMID 33374841, 2020). "The current study agrees with previous observations showing that TRPV1 and TRPA1 channels play an important pronociceptive role in the painful diabetic neuropathy and extends these observations to TRPC channels." (PMID 30602386, 2019). "Modulation of the TRP channels TRPA1 and TRPV1 has been implicated in both neuronal damage and pain in diabetic neuropathy." (PMID 29930087, 2018). "Transient receptor potential (TRP) channels such as TRPA1 and TRPV1 are implicated in both the pain and neuronal damage in diabetic neuropathy." (PMID 29930087, 2018). "Recently, GRC 17536, another TRPA1 antagonist, showed positive data in a Phase IIa proof of concept study in patients with painful diabetic neuropathy." (PMID 28894590, 2017). "In September 2014, Glenmark announced that GRC 17536, a peripherally acting selective TRPA1 antagonist, exhibited efficacy in a phase 2a proof-of-concept study in patients with painful diabetic neuropathy." (PMID 25640188, 2015). "More recently, Glenmark Pharmaceuticals Ltd. reported that GRC 17536, a peripheral acting TRPA1 antagonist, exhibited efficacy in a phase 2a proof-of-concept study in patients with painful diabetic neuropathy." (PMID 25640188, 2015). "Reactive oxygen species and electrophilic metabolites are potent endogenous TRPA1 agonists and are important for the development of diabetic neuropathy." (PMID 24167592, 2013). "Andaliman extract potentially serves as a therapy for diabetic neuropathy in T2DM by lowering BGL and inhibiting the expression of TNF-α and TRPA-1." (PMID 39101085, 2024). "Notably, the TRPA1 antagonist GRC17536 demonstrated a significant reduction in the pain score among patients with painful diabetic polyneuropathy in the non-denervated group, without any adverse effects." (PMID 37569884, 2023). "A phase 2a clinical study yielded data indicating that the TRPA1 antagonist, GRC 17536, alleviates pain with no other drug-related side effects in patients with painful diabetic neuropathy, which supports the promising therapeutic efficacy of TRPA1 blockade in pain management." (PMID 32256338, 2020).
diabetic neuropathy (continued). "Another TRPA1 antagonist, oral GRC17536, was able to finish a phase II clinical trial as a promising treatment for diabetic neuropathy but was not able to advance to phase III, due to its limited bioavailability and pharmacokinetic profile." (PMID 37511138, 2023).
inflammatory bowel disease (19 papers, 2014 to 2025). A spectrum of small and large bowel inflammatory diseases of unknown etiology. "Altered TRPA1 function is associated with gastrointestinal disorders such as inflammatory bowel disease (IBD)." (PMID 39022308, 2024). "Antagonism of transient receptor potential vanniloid-1 (TRPV1) and desensitization of transient receptor potential ankyrin-1 (TRPA1) nociceptors alleviate inflammatory bowel diseases (IBD)-associated chronic pain." (PMID 36076974, 2022). "TRPA1 is also reported to be upregulated in Inflammatory Bowel Disease patients and plays a crucial role in the inflammatory response of Inflammatory Bowel Disease." (PMID 37039840, 2023). "Among the preclinical disease models, TRPA1 is involved in almost all painful or pruritic disorders, prominently in respiratory (cough), pancreatic, and inflammatory bowel disease (IBD) models." (PMID 35157132, 2022). "As TRPA1 channels are present on capsaicin-sensitive sensory neurons, they have also shown involvement in inflammatory bowel disease (IBD) along with TRPV1 channels." (PMID 34912298, 2021). "The proposed protective roles of TRPA1 indicate future prospects in inflammatory bowel diseases research." (PMID 25265225, 2014). "Dysregulation of TRPA1 been implicated in various gastrointestinal disorders including irritable bowel syndrome (IBS), inflammatory bowel disease (IBD), and functional dyspepsia, contributing to visceral hypersensitivity, inflammation, and disturbances in gastric motility." (PMID 39022308, 2024). "Although some of the experiments were performed on tissues from the porcine jejunum, the primary focus was on the colon as a major locus of fermentation and of inflammatory bowel disease, which also happened to be the tissue with the highest expression of mRNA for TRPA1." (PMID 34068986, 2021). "Taken together, a TRPA1-based modulation of inflammatory bowel disease could be therapeutic, but clinical trials are still missing." (PMID 31547502, 2019). "In inflammatory bowel disease, the evidence regarding TRPA1 involvement is far from unequivocal." (PMID 31547502, 2019). "TRPA1 is implicated in abdominal pain and hypersensitivity in irritable bowel syndrome (IBS) and Inflammatory Bowel Disease (IBD)." (PMID 39022308, 2024). "Upregulation of TRPA1 was reported in patients with inflammatory bowel disease (IBD), but the role of TRPA1 in IBD is still controversial." (PMID 33810314, 2021). "Importantly, TRPA1 expression was previously shown to be increased on leukocytes such as monocytes and lymphocytes in other inflammatory conditions including in LPS challenge and inflammatory bowel disease." (PMID 28239353, 2017). "Many conditions beyond temporal pain show the potential for TRPA1 antagonists to reduce hyperalgesia such as rheumatoid arthritis, endometriosis, and IBD (inflammatory bowel disease)." (PMID 39301325, 2024). "The TNF-α level in the peripheral blood mononuclear cell supernatants of patients with inflammatory bowel disease (IBD) is elevated, and the presence of TRPA1 antagonists abolishes the inflammatory effects of TNF-α." (PMID 36875034, 2023). "TRPA1 and TRPV1 expressions were investigated in human colon biopsies of healthy subjects and patients with inflammatory bowel diseases (IBD: ulcerative colitis, Crohn's disease) with quantitative PCR and immunohistochemistry." (PMID 25265225, 2014).
lung carcinoma (19 papers, 2018 to 2025). "Currently, only a few channels of the TRP family have been characterized as having a role in tumor angiogenesis, such as TRPV4, TRPV3, TRPM3, and TRPA1, demonstrated in lung carcinoma, renal cell carcinoma, cancer-associated fibroblast, and prostate cancers." (PMID 37576552, 2023). "In Lewis lung cancer cells, the expression of TRPA1 and TRPM8 is linked with autophagy, tumor cell metastasis, and energy metabolism." (PMID 36090899, 2022). "Under hypoxic conditions, TRPA1 suppresses invasion in lung cancer cells in vitro, whereas in breast and lung cancer spheroids, it enhances resistance to reactive oxygen species (ROS) and activates Ca2+-dependent anti-apoptotic signaling pathways." (PMID 41155636, 2025). "In lung cancer, TRPA1 expression positively correlates with higher cancer stages and metastases and indicates higher risk." (PMID 39770499, 2024). "By using a more physiological context, the authors unveiled an increase in ROS production in the inner region of breast and lung cancer spheroids, which led to TRPA1-mediated Ca2+ entry and resistance to oxidative stress." (PMID 37174661, 2023). "A subsequent report, however, showed that FGFR2 expression is rather low in TRPA1-expressin lung cancer cells and that the TRPA1–FGFR2 interaction is likely to be a rare event in LUAD." (PMID 37174661, 2023). "The distinct outcome of ROS-dependent TRPA1 activation in different cancer types, e.g., survival in breast and lung cancers and apoptosis in mCRC and glioblastoma multiforme, is likely to be associated to the heterogeneity of TRPA1-mediated Ca2+ signals." (PMID 37393347, 2023). "Takahashi and coworkers recently carried out a systematic investigation to assess the role of extracellular Ca2+ entry through TRPA1 in the engagement of an antioxidant defense program in breast and lung cancer cells." (PMID 37174661, 2023). "In breast and lung cancer, ROS-induced TRPA1 activation leads to intracellular Ca2+ oscillations that engage antioxidant and pro-survival signaling pathways, resulting in cancer cell tolerance to oxidative stress." (PMID 37174661, 2023). "In the TRPA1 gene overexpression (upregulated) in Nasopharyngeal Carcinomaand contribute to the development of lung cancer." (PMID 32986378, 2020). "A functional expression of TRPA1 in lung cancer cells has been detected in a broad panel of SCLC cell lines." (PMID 30248976, 2018). "In addition, astrocytes release exosomes containing miR-142-3p, which downregulates the expression of transient receptor potential ankyrin-1 (TRPA1) in lung cancer cells, thereby disrupting the TRPA1–FGFR2 axis and inhibiting tumor progression and metastasis." (PMID 41429896, 2025). "Our findings suggest that the inhibition of RHCG and TRPA1 enhances the sensitivity of lung cancer cells to radiation and may provide a new target for the combination of radiotherapy and immunotherapy for lung cancer treatment." (PMID 38430394, 2024). "Experimental validation of signature genes in the CS2 subtype showed that inhibiting the expression of RHCG and TRPA1 could enhance the sensitivity of lung cancer cells to radiation." (PMID 38430394, 2024). "In agreement with in vitro findings, this study demonstrated that genetic or pharmacological blockade of TRPA1 retarded breast and lung cancer growth and suppressed chemoresistance in immunocompromised mice and confirmed that tumor cells were also exposed to higher oxidative stress in vivo." (PMID 37174661, 2023). "Here, we investigated whether the TRPA1 channel is involved in the cytotoxicity of acrolein in human lung cancer A549 cells." (PMID 37511605, 2023). "Therefore, TRPA1 activation in mCRC cells supports ROS-dependent apoptosis rather than cell survival, as otherwise reported in breast and lung cancers." (PMID 37393347, 2023). "Additionally, TRPA1-mediated Ca2+ entry promoted breast and lung cancer cell resistance to ROS-producing chemotherapeutics, such as carboplatin, doxorubicin, and paclitaxel." (PMID 37174661, 2023).
lung carcinoma (continued). "Finally, the authors demonstrated that TRPA1 expression in breast and lung cancer cells was regulated by NRF2, which can therefore prevent ROS-induced apoptosis by inducing the expression of both canonical (e.g., antioxidant) and non-canonical (e.g., TRPA1) oxidative stress defense proteins." (PMID 37174661, 2023). "Furthermore, it has been found that elimination of Schwann cell TRPA1 attenuates lung cancer-induced mechanical allodynia, and therefore, Schwann cell TRPA1 may represent a potential target for the treatment of cancer pain." (PMID 37039840, 2023). "TRPA1 may have predictive relevance in lung cancer, according to our findings." (PMID 36090899, 2022). "Intriguingly, the same approach demonstrated that TRPA1 mediated H2O2-evoked intracellular Ca2+ oscillations in breast and lung cancer cell lines." (PMID 37174661, 2023). "TRPA1 induced autophagy under adverse conditions, and the combination of TRPM8 and TRPA1 directly contributed to the aggressive phenotype of lung cancer." (PMID 35281822, 2022). "Genetic silencing of NRF2 reduced TRPA1 expression in lung cancer cell lines, while it did not affect the expression levels of other TRP isoforms, such as TRPC3 and TRPV1." (PMID 37174661, 2023). "TRPA1 is expressed and functions in neuronal cells, but a few reports have shown that its expression is also induced in non-neuronal cells, including lung cancer cell lines and bronchial epithelial cells, by cigarette smoke extract (CSE)." (PMID 37511605, 2023). "Knockdown of TRPA1 promoted LLC-2 cell proliferation and invasiveness of lung cancer." (PMID 35281822, 2022). "Furthermore, it has been reported that MMP1, HMGA2, TRPA1, and PLAU are highly expressed in various subtypes of lung cancer." (PMID 35354498, 2022).